BRCA1 (BRCA1 DNA repair associated)
Diseases named in the same sentence as BRCA1 in open-access papers (continued):
Sharing a sentence is not in itself a finding about the gene and the disease.
leukemia (continued). "We also found mutations in genes with no reported association to the diagnosis of the patient, such as BRCA1 and PTCH1 mutations in neuroblastoma, as well as PMS2 mutations in leukemia." (PMID 33674644, 2021). "BRCA1 and BRCA2 mutations increased leukaemia (RR 2.3 [1.21–4.39] and 1.79 [1.03–3.12], respectively)." (PMID 34577828, 2021). "To further explore the prognostic value of BRCA1 in leukemia and validate our model, we downloaded 151 patient expression and clinical profiles from The Cancer Genome Atlas (TCGA) for acute myeloid leukemia." (PMID 32615918, 2020). "There are only limited data on the role of BRCA1 activation in leukemia, higher BRCA1 expression was found in resistant AML sample." (PMID 31384395, 2019). "Combination of PARPi and RAD52i also effectively eliminated primary leukemia cells displaying “BRCA1/2-ness”, while individual compounds generated only a partial effect." (PMID 31615159, 2019). "Five of these compounds representing 3 different chemotypes selectively inhibited growth of BRCA1-, BRCA2-deficient human cancer cells and BRCA1-deficient (with low expression level) primary cells from leukemia patients." (PMID 27649245, 2016). "Both BRCA1 and BRCA2 mutation positive families included cases of leukemia that accounted for about 2 percent of affected individuals." (PMID 18783588, 2008). "Because of connections between Fanconi proteins and leukemias, these relationships further implicate BRCA1/BRCA2 deficits in leukemias." (PMID 17683622, 2007). "In chronic myelogenous leukemia (CML) cells, BRCA1 is also down regulated, becoming nearly undetectable in leukemia cells from patients during chronic phase and blast crisis." (PMID 17683622, 2007). "This work shows that the pathway containing BRCA1/2 gene products is essential to prevent a group of leukemias and lymphomas." (PMID 17683622, 2007). "As leukaemias are among malignancies with the highest methylation density, we studied regulation of BRCA1 expression by promoter hypermethylation." (PMID 17047656, 2006). "Analogous to BRCA1, loss of ZNF292 function might impair DNA damage repair, theoretically increasing susceptibility to solid tumors or leukemias." (PMID 40777882, 2025). "A study by Garcia and others (2017) found that adavosertib impairs HR and may work as a combination therapy with PARP inhibitor olaparib in BRCA1/2-mutant leukemias." (PMID 36081565, 2022). "BRCA1 and BRCA2 mutations can increase leukaemia incidence based on three studies." (PMID 34577828, 2021). "The authors proposed to use the F79 aptamer to treat leukemias displaying low levels of BRCA1/2." (PMID 31615159, 2019). "Additionally, F79 treatment induced synthetic lethality in BRCA1/2-mutated breast, pancreatic, and ovarian cancer cells and exerted synergistic effects with imatinib (approved for BCR-ABL1-positive leukemia) and ATRA (for PML-RAR-positive leukemia)." (PMID 36980703, 2023). "Although leukemia has not been recognized as a typical BRCA1/2-mutated cancer, our group and others have recently reported that certain types of leukemias and other hematopoietic malignancies display HR with/without concomitant c-NHEJ functional deficiency caused by leukemia-inducing mutations." (PMID 36497275, 2022). "Family history of leukemia was observed in patients carrying a VUS in the ATM, BRCA1 and BRCA2 genes." (PMID 37277882, 2023). "In contrast, recent studies have shown that in BRCA-proficient leukemia cells, inhibition of the TGFβ pathway promotes a reduction in ATM, BRCA1 and BRCA2 and a concomitant increase in olaparib sensitivity." (PMID 34871431, 2021). "TIAR is a component of cytoplasmic SGs that affects the ARE site in BRCA1 mRNA and can result in its down-regulation in BCR-ABL1 leukemia, which leads to genomic instability." (PMID 34604242, 2021).
leukemia (continued). "We confirmed BRCA1 and NSD2 involved not only in leukemia cell differentiation but also tumorigenesis via regulating c-Myc." (PMID 32826945, 2020). "Ectopic expression of BRCA1 resulted in reversion of sensitivity to AICAR in Capan1 and BCR-ABL1 leukemia cells implicating the synthetic lethal interactions between BRCA-deficiency and AICAR." (PMID 31615159, 2019). "The present study was designed to test the hypothesis that inactivation of virtually any component within the pathway containing the BRCA1 and BRCA2 proteins would increase the risks for lymphomas and leukemias." (PMID 17683622, 2007).
glioblastoma (39 papers, 2008 to 2025). The most malignant astrocytic tumor (WHO grade IV). "Recently, the implementation of TTF in glioblastoma treatment was associated with the downregulation of breast cancer type 1 susceptibility protein (BRCA1) signaling and the reduction in DNA double-strand break repair capacity." (PMID 35954371, 2022). "Recently, scientists also found that Id4 is involved in the suppression of matrix metalloproteinase 2 (MMP2)-mediated cell invasion in glioblastoma and also in the modulation of miR-342-regulated breast cancer type 1 susceptibility protein (BRCA1) expression." (PMID 31847356, 2019). "Few cases of glioblastoma in BRCA1 mutation carriers were reported but the BRCA1 expression status has never been studied." (PMID 25880076, 2015). "Our data show that BRCA1 expression is maintained in glioblastoma at the protein and the mRNA levels, suggesting that loss of heterozygosity (LOH) did not occur in these cases." (PMID 25880076, 2015). "In an attempt to clarify the role played by a mutated BRCA1 allele in the GBM development, we investigated the BRCA1 mRNA and protein expression in breast and glioblastoma tumours for both patients." (PMID 25880076, 2015). "In an attempt to clarify the role played by a BRCA1 mutation in GBM development, we performed diverse molecular experiments to characterize the expression status of BRCA1 in glioblastoma, and in the first TNBC of the two patients." (PMID 25880076, 2015). "BRCA1, traditionally considered a tumor suppressor, plays an unexpected tumor-promoting role in glioblastoma." (PMID 38977680, 2024). "Another study in glioblastoma showed that BRCA1 regulates RRM2 expression via E2F1, and RRM2 inhibition mimics the phenotype of BRCA1-loss in glioblastoma cells." (PMID 38124207, 2023). "In contrast, four patients had progressive disease (PD); two patients with glioblastoma harboring BRCA1 c.5153-1G > C and BRCA2 p.S1982fs received a PARP inhibitor (veliparib and olaparib) and had PD after 1.4 and 0.2 months, respectively." (PMID 38143440, 2023). "High expression of BRCA1 has been shown to correlate with lower overall survival in glioblastoma patients, underscoring the need to investigate treatments that can dysregulate BRCA1 signaling." (PMID 34207158, 2021). "We have shown that VRK1 depletion sensitizes tumor cells to two types of pharmacological treatments, temozolomide, a drug used in glioblastoma, and olaparib, an inhibitor of PARP-1 that is in use for the treatment of tumors with BRCA1 mutations." (PMID 34195200, 2021). "BRCA1 is usually considered a tumor suppressor, but in glioblastomas, BRCA1 helps to mitigate replication stress and extend cancer cell survival." (PMID 34207158, 2021). "BRCA1-regulated RRM2 expression protects glioblastoma cells from endogenous replication stress and promotes tumorigenicity." (PMID 31886214, 2019). "Here, the authors find that BRCA1 promotes the expression of RRM2 protecting glioblastoma cells from replication stress, DNA damage and apoptosis." (PMID 27845331, 2016). "Here we report that BRCA1, traditionally regarded a tumour suppressor, plays an unexpected tumour-promoting role in glioblastoma (GBM), safeguarding a protective response to supraphysiological RS levels." (PMID 27845331, 2016). "Here we report two cases of BRCA1 mutated patients who developed a glioblastoma multiform (GBM)." (PMID 25880076, 2015). "Similarly, in our experiments, LCS1269 affected p-Chk1 (Ser345) and p-BRCA1 (Ser1524) phosphorylation levels in a dose-dependent manner in both glioblastoma cell lines, U251 and T98G, whereas p-Chk2 (Thr68) phosphorylation was increased only in U251 cells." (PMID 40649791, 2025).
glioblastoma (continued). "Indeed, in glioblastoma-derived cells, BRCA1 knockdown downregulates RRM2, a catalytic subunit of ribonucleotide reductase, leading to replication stress and DNA damage, and ultimately suppressing cell proliferation." (PMID 33888730, 2021). "Other pathways, such as the upregulation of BRCA1 by SPT6 in glioblastoma cells, could contribute to the suppression of replication stress." (PMID 34233157, 2021). "Our data show that the BRCA1 protein expression is maintained in glioblastoma suggesting that no loss of heterozygosity occurred in these tumours." (PMID 25880076, 2015). "We have clarified the signaling and metabolic pathways (i.e. role of BRCA1 in DNA damage response), networks (i.e. cell cycle) and biological processes (i.e. cell division process of chromosomes) that result from hHSS1effects upon glioblastoma growth." (PMID 25481245, 2014). "Importantly, for the remaining nine PGVs that were identified in genes with a strong association with familial glioblastoma or medulloblastoma (SUFU, MSH6 (2x), PMS2 (5x) and BRCA1), a second (somatic) event and/or a matching mutational signature was identified in the tumor." (PMID 41168197, 2025). "Finally, paired glioblastoma cell lines deficient or not in DNA-PK were employed to probe the potential requirement of the latter in BRCA1 downregulation." (PMID 21103343, 2010). "Editing levels of the Alu element sites in BRCA1 gene were increased, and those of the coding sequences in CYFIP2 and FLNA genes were reduced in glioblastoma multiforme brain tissue." (PMID 22859999, 2012). "We suggested that the increased transcription of BRCA1, ATM, and DNA-PK might counteract the MGMT depletion induced by AE and TMZ treatment of glioblastoma cells." (PMID 37630276, 2023). "Since BRCA1 is dependent on CDK9 for HR repair, CDK9 inhibition may provide a synthetic lethal mechanism to render glioblastomas more vulnerable to PARP inhibitors." (PMID 34207158, 2021). "Additionally, the study showed downregulation of BRCA1 and MMR-dependent ABL1 gene expression in IMR-90 cells in comparison to the increased expression of BRCA1 and ABL1 in glioblastoma cells; indicating involvement of the HRR and MMR pathways." (PMID 28703770, 2017). "Thus, conserved BRCA1 protein expression in glioblastoma does not completely rule out its role in GBM development." (PMID 25880076, 2015). "TMZ- or IR-induced nuclear accumulation of BRCA1 in IN-GB-2 cells, but not in IN-GB-10 cells, provided further evidence for the enhanced HR activity of the TMZ-resistant IN-GB-2 glioblastoma cells." (PMID 28852018, 2017). "Indeed, Elmariah and co-authors reported the case of a patient mutated for BRCA1 who developed glioblastoma but they did not investigate BRCA1 mRNA and protein expression in the GBM." (PMID 25880076, 2015).
fallopian tube cancer (38 papers, 2004 to 2026). A primary or metastatic malignant neoplasm that affects the fallopian tube. "The ML analysis identified CA125 levels, patient age, and MatoRRSO as primary risk factors for ovarian and fallopian tube cancers in BRCA1 and BRCA2 mutation carriers, consistent with current clinical understanding." (PMID 40303993, 2025). "The only strategy shown to decrease the incidence and mortality from ovarian and tubal cancer in BRCA1/BRCA2 P/LP variant carriers was RRSO." (PMID 39858629, 2025). "PDX TM00089 is derived from a patient with a germline pathogenic v757fs*BRCA1 mutation (truncation) who had received prior cisplatin/taxol therapy for a fallopian tube carcinoma (; Mouse Models of Human Cancer Database, Jackson Research Labs)." (PMID 39819384, 2025). "Preventive strategies for tubal cancer, particularly for women at high risk due to genetic predispositions such as BRCA1 or BRCA2 mutations, often focus on risk-reducing salpingo-oophorectomy (RRSO)." (PMID 39274288, 2024). "We also performed prophylactic salpingo-oophorectomy to prevent ovarian and fallopian tube cancers in patients with BRCA1/2 gene variants." (PMID 38854450, 2023). "In other words, there is a 79% risk reduction in ovarian and fallopian tube cancers in pathogenic BRCA1/2 carriers with risk-reducing surgery." (PMID 35190596, 2022). "One of the first studies to link BRCA germline mutations with STICs was published back in 2000, which demonstrated “fallopian tube cancer” in two patients with BRCA1 germline mutations who also had loss of the wild-type BRCA1 allele in the tumor tissue." (PMID 32069831, 2020). "The incidence of occult ovarian/fallopian tube cancers in patients having undergone prophylactic surgeries for BRCA1 gene mutation is varied and ranges from 1.9% to 16.2%." (PMID 28182133, 2017). "One recurrent BRCA1 (c.3607C>T) mutation was detected in one BC and tubal cancer patient and in one OC patient." (PMID 28961279, 2017). "Furthermore, a phase Ib clinical trial is evaluating the combination of niraparib and copanlisib, a PI3K inhibitor, in BRCA1/2-mutated ovarian, endometrial, or fallopian tube cancer (NCT03586661)." (PMID 40274769, 2025). "Another study performed on 108 patients with fallopian tube cancer identified 21% of patients with a mutation in BRCA1 and 9% in BRCA2, whereas one study performed on 79 patients with peritoneal/fallopian tube cancer identified mutations in BRCA1/BRCA2 in 23% of the patients." (PMID 27532258, 2016). "Approximately 30% of women with fallopian tube cancer have a mutation in BRCA1 or BRCA2." (PMID 26090245, 2015). "Fallopian tube cancer has been reported in BRCA1 and BRCA2 germline mutation carriers recently." (PMID 15083174, 2004). "Meta-analysis of risk reduction estimates associated with risk-reducing salpingo-oophorectomy (RRSO) in BRCA1 or BRCA2 mutation carriers indicated that RRSO was associated with a statistically significant reduction in the risk of BRCA1/2-associated ovarian or fallopian tube cancer (HR 0.21)." (PMID 38275400, 2024). "Whereas our estimation of the contribution of BRCA2 germline mutations for peritoneal/fallopian tube cancers in hospital-based cohorts is likely to be reliable, the evaluation of the contribution of BRCA1 mutations may require additional larger studies that include full gene analysis." (PMID 27532258, 2016). "Furthermore, PBSO was associated with a statistically significant reduction in the risk of BRCA1/2-associated ovarian or fallopian tube cancer; however, data were deemed insufficient to obtain separate estimates for ovarian or fallopian tube cancer risk reduction." (PMID 20961453, 2010). "Out of 496 healthy BRCA1/2 carriers, eleven (2.2%) OC were detected (four serous tubal intraepithelial cancers and seven invasive ovarian/fallopian tube cancers)." (PMID 36831416, 2023). "In BRCA1 mutation carriers, delaying RRSO beyond 40 years is associated with an increased risk of developing OC or tubal cancer." (PMID 36837501, 2023).
fallopian tube cancer (continued). "The majority of BRCA mutations are located in the BRCA1 gene and the BRCA2 gene mutations comprise fewer cases and the latter also demonstrates a smaller risk for early fallopian tube carcinomas." (PMID 35147976, 2022). "A detailed analysis of BRCA1 carriers showed ovarian and fallopian tube cancer diagnosed in the postoperative material in 3 out of 83 cases (3.6%)." (PMID 28182133, 2017). "Patients with BRCA1 or BRCA2 pathogenic variants should consider risk-reducing bilateral salpingo-oophorectomy after child-bearing or between the ages of 35–40 years to reduce ovarian and fallopian tube cancer risk." (PMID 31342359, 2019). "At inclusion, 56.3% of BRCA1 female PV carriers were diagnosed with BC (mean age at diagnosis: 41.3, range 22–81), 18.3% were diagnosed with OC or fallopian tube cancer (mean age at diagnosis: 51.9, range 16–92) and 33.2% were free of these cancers (mean age at inclusion: 40.5, range 18–101)." (PMID 30430080, 2018). "In the 33 patients with peritoneal/fallopian tube cancer analyzed, none was carrier of the BRCA1 c.3331_3334del mutation and one patient (3.0%) was a carrier of the BRCA2 c.156_157insAlu mutation." (PMID 27532258, 2016). "In 2018, the SOLO-1 trial randomized 391 patients with BRCA1 and/or BRCA2 mutation, FIGO Stage III or IV high-grade serous or endometrioid ovarian/primary peritoneal/fallopian tube cancer, regardless of surgical outcome and/or complete/partial response after first-line platinum-based chemotherapy." (PMID 38931448, 2024). "In the series of 33 peritoneal/fallopian tube cancers analyzed, we identified only one patient (3.0%) carrying the BRCA2 c.156_157insAlu mutation (estimated total contribution of BRCA2 mutations of 5.5%) and no carriers of the BRCA1 c.3331_3334del mutation." (PMID 27532258, 2016).